KRAS (KRas proto-oncogene, GTPase)
Diseases named in the same sentence as KRAS in open-access papers (continued):
Sharing a sentence is not in itself a finding about the gene and the disease.
colon carcinoma (continued). "To confirm the association between KRAS genotype and ixazomib sensitivity, we used SW48 isogenic colon cancer cell lines." (PMID 26709701, 2015). "These compounds selectively inhibited (100-fold) the growth of KRAS mutant HCT116 colon cancer cells compared to primary rat hepatocytes, while also decreasing KRAS protein levels." (PMID 26024321, 2015). "Based on previous results, IQc 2d, 3d and 3e were selected to study effects on those colon cancer cells expressing mutant KRAS (HCT116 and metastatic SW620)." (PMID 25853628, 2015). "We have previously demonstrated that miRNA-143, which also reduces KRAS expression, chemosensitizes colon cancer cells to 5-fluorouracil, and reduces tumor growth in vivo, with increased apoptosis and reduced proliferation." (PMID 26024321, 2015). "We investigated this by knockdown of SWI/SNF complex members in the colon cancer cell line HCT116, which harbours an activating KRAS G13D mutation (KRASG13D/+), and in a derived cell line in which the mutant KRAS allele was deleted (KRASKO/+)." (PMID 25748138, 2015). "Exosomes have also been shown to transport mutant KRAS proteins to colon cancer cells, increasing tumor growth." (PMID 26177391, 2015). "The present study revealed that tumour dissemination is less likely to occur in colon cancer patients with MSI and BRAF mutation, whereas the presence of a KRAS mutation increases the likelihood of disseminated disease." (PMID 25884297, 2015). "To further explore the connection between KRAS genotype and ixazomib sensitivity in vivo, we used a set of colon cancer cell lines which differ in KRAS status but are otherwise genetically matched." (PMID 26709701, 2015). "This is in line with a recent report showing the positive effect of TAK1 on β-catenin stabilization and nuclear localization in KRAS-dependent colon cancer cells." (PMID 24728340, 2014). "In the in-vitro study, we firstly demonstrated that KRAS mutant colon cancer cells are more sensitive to oxaliplatin than the same KRAS mutant colon cancer cells in which the expression of mutant KRAS was knocked down by small interfering RNA (siRNA)." (PMID 24505265, 2014). "Oncogenic pathways (KRAS/BRAF in colon cancer) circumvent the canonical HH-GLI axis by converging on and further driving GLI to a higher activating state in tumor cells, promoting cellular proliferation, tumor progression and survival." (PMID 24962990, 2014). "Mutations in the v-Ki-ras2 Kirsten rat sarcoma viral oncogene homolog (KRAS), which occur most frequently in codons 12, 13, and 61, are found in ∼40% of colon tumors 14–16." (PMID 24668895, 2014). "These enhancements were also observed in another colon cancer cells line HCT-116, which also has a KRAS mutation." (PMID 25427200, 2014). "Activating mutations in both KRAS and BRAF are prevalent, and occur in high frequency in colon cancers." (PMID 24962990, 2014). "IGF1R and KRAS targeting by let-7d-5p and 3p was further experimentally validated since the two miRNA species were differentially expressed in colon cancer cells in reverse directions: let-7d-5p was up-regulated whereas let-7d-3p was down-regulated." (PMID 25287248, 2014). "In colon cancer cells oncogenic KRAS-GLI signaling circumvents the HH-SMO-GLI axis to channel through and activate GLI in the transcriptional regulation of target genes." (PMID 24962990, 2014). "The use of KRAS mutational status to determine response to anti-EGFR therapies (e.g. cetuximab and panitumumab) is the paradigm of stratified patient selection in colon cancer." (PMID 25074435, 2014). "Activating mutations in KRAS, and to a lesser extent, its downstream effector BRAF, are frequent events in colon cancer." (PMID 24498230, 2014).
colon carcinoma (continued). "We observed many KRAS (52.9%), PIK3CA (12.4%), and NRAS (7.4%) mutations in a colon cancer tissue collection (N = 121)." (PMID 24658394, 2014). "KRAS status is presently the only biomarker routinely used to select patients with colon cancer for EGFR inhibition-targeted therapy, which is widely used to treat metastatic colorectal cancer." (PMID 25297496, 2014). "Activating mutations of oncogenes such as KRAS, BRAF or PIK3CA that are common to colon cancer have been reported to be associated with resistance to cytotoxic agents or molecularly targeted drugs." (PMID 23852390, 2013). "Here, we report the identification of ISC-4 and cetuximab as a promising combination therapy that has synergistic anti-tumor activity in vitro and in vivo against human colon cancers harboring a wild-type KRAS gene." (PMID 23555026, 2013). "In a study of colon cancer xenografts, there was concordance between gene copy number and mutation (NRAS, KRAS, BRAF, PIK3CA) in first- and second-generation xenografts and in the parent tumor." (PMID 23981300, 2013). "Cumulatively, these efficacy and safety data indicate that the combinatorial activity of cetuximab and ISC-4 should be evaluated in future clinical trials with 5-FU-refractory colon cancer harboring wild-type KRAS genes." (PMID 23555026, 2013). "Stable transformation of colon cancer cells with KRAS increased DNA methyltransferase activity and P16 gene methylation." (PMID 23509688, 2013). "We have tested a battery of melanoma and colon carcinoma cell lines that carry mutations in BRAF, NRAS and KRAS genes and have observed that those with NRAS and KRAS mutations are more sensitive to killing by IPA3." (PMID 22869096, 2012). "Taken together, these results show an increase in MAPK/PI3K signaling and an overexpression of Abi1 upon transfection of wild-type HDC-9 colonic carcinoma cells with constitutively active KRAS G12D." (PMID 22808230, 2012). "These included mutations in KRAS and APC, two somatic genetic changes frequently observed in colon cancer." (PMID 21738606, 2011). "More specifically, mutant KRAS disrupts actin cytoskeleton and maintains motility in colon cancer cells." (PMID 21943101, 2011). "To compare the efficiency of the drug combination in CC cells with wild-type KRAS, we analyzed the apoptotic response of the human colon cancer cells SW48 cells." (PMID 22073312, 2011). "Given the failure of antiEGFR monoclonal antibodies to demonstrate a benefit in the adjuvant setting for stage III WT KRAS colon cancer, the value of further study of these agents for rectal cancer is doubtful." (PMID 21437184, 2011). "The KRAS mutation in our retrospective study came forward as a negative predictive factor for OS in patients with rectal cancer and for DFS in stage II colon cancer patients (trend)." (PMID 20959826, 2010). "To decipher the possible genetic reasons underlying the high incidence of colon cancer in AAs, we earlier conducted studies on the MSI, methylation of CAN genes and mutations of known genes such as BRAF and KRAS." (PMID 20126641, 2010). "Several large randomized-controlled trials demonstrated no benefit from expensive anti-EGFR drugs such as cetuximab (ErbituxTM) in patients with KRAS-mutant colon cancer." (PMID 21110880, 2010). "Many tumors contain only a KRAS or BRAF mutation, which is consistent with previous reports finding these mutations in earlier stages of colon cancer." (PMID 20233444, 2010).
colon carcinoma (continued). "The National Comprehensive Cancer Network (NCCN) now recommends KRAS testing prior to initiation of anti-EGFR therapy in colon cancer patients." (PMID 21110880, 2010). "OncoCarta assays interrogate 99%, 98%, and 78% of the known colon cancer mutations in BRAF, KRAS, and PIK3CA, respectively, based on a large number of colon cancer samples that have been sequenced in BRAF (n = 4628), KRAS (n = 858) and PIK3CA (n = 247)." (PMID 20233444, 2010). "Levels of GTP bound-K-ras were induced by hypoxia in colon cancer cells with wild-type KRAS (Caco2, HT29) whereas there were no changes in cell lines with a mutant KRAS oncogene (DLD1, HCT116, SW480)." (PMID 20532039, 2010). "Hypoxia is thus a strong activator of Ras in colon cancer cells, but this induction was observed only in those cells with a wild-type KRAS gene." (PMID 20532039, 2010). "Hypoxia consistently increased the levels of activated, GTP-bound K-ras in colon cancer cell lines with a wild-type KRAS gene, and this depended upon the activation of c-Src." (PMID 20532039, 2010). "The colon cancer cell line HCT116, in addition to KRAS mutation, also harbors an activating mutation in the RAS effector PIK3CA." (PMID 19492075, 2009). "We find that in colon cancer cells harboring a KRASG13D mutant allele, knocking down KRAS alone or the RAFs in combination or the RAF effectors, MEK1 and MEK2, together is effective in delaying tumor growth in vivo." (PMID 19492075, 2009). "Alternatively, downstream pathways can become constitutively activated, an example being KRAS, which has been reported in lung and colon cancers." (PMID 17875215, 2007). "Thus, although haploid HAP1 cells are the primary models for SGE, the successful application of SGE to diploid HCT 116 colon carcinoma cells provides a practical framework for implementing SGE in KRAS-dependent carcinoma cells." (PMID 42042001, 2026). "Studies have explored the correlation between KRAS mutation and COX-2 overexpression in colorectal tumors and colon cancer cell lines, revealing that the activation of mutated KRAS increases COX-2 expression by enhancing the activity of mitogen-activated protein kinases (MAPKs)." (PMID 40943367, 2025). "Cell culture studies also report that HIF inhibition may be effective in the treatment of KRAS mutant colon cancer." (PMID 39996842, 2025). "In colon cancer, KRAS mutation has been identified as a strong negative predictive biomarker that confers resistance to EGFR inhibitors." (PMID 41523436, 2025). "Consistent with this, genetically engineered mouse models show that ALK4 deletion in combination with oncogenic KRAS drives pancreatic tumorigenesis, and CRISPR-Cas9-mediated ALK4 depletion enhances colon cancer tumorigenicity in the presence of APC and KRAS mutations." (PMID 41408046, 2025). "Other groups have reported similar observations in KRAS mutant colon cancer cells." (PMID 40802750, 2025). "In addition, the colon cancer cell line HCT-116 further confirmed that RBP inhibited the interaction between G13D KRAS and RAF, as compared to HT-29 cells with wild-type KRAS." (PMID 40236954, 2025). "In KRAS-mutated colon cancer cells, SLC25A22-mediated Gln breakdown reduces H3K4me3 methylation, stimulates the activation of the Wnt/beta-catenin signaling pathway, and diminishes the sensitivity of colon cancer cells to chemotherapeutic agents." (PMID 40276500, 2025). "In contrast, the majority of the lesions in the KRAS-WT subgroup and adjacent normal colon tissues exhibited weak or no REGγ staining, indicating a pattern of specific REGγ expression in KRAS-mutant colon cancers." (PMID 40091835, 2025).
colon carcinoma (continued). "Notably, mutations in the cancer-associated genes KRAS G12D (spontaneous thymic T lymphoma) and Ctnnb1 G34E (AOM-induced colon cancer) were detected in two of the four tumors." (PMID 40734673, 2025). "However, genetic silencing of the gene encoding MEK2 using short hairpin RNAs inhibits the proliferation of human colon carcinoma cell lines HCT116 and HT29, which harbor mutations in KRAS and BRAF." (PMID 38277448, 2024). "Similarly, the transfer of the mutated KRAS gene, along with other oncogenes such as EGFR, from colon cancer cells to recipient cells with wild-type KRAS occurs through exosomes, promoting tumor invasion." (PMID 38672455, 2024). "BRAFV600E, KRAS G12C, and G13D mutations are linked to shorter survival after recurrence (SAR) in patients who underwent surgery for stage III microsatellite stable (MSS) colon cancer." (PMID 39682117, 2024). "The survival rate of stage II dMMR colon cancer patients with high-risk factors is similar to that of patients without high-risk factors, regardless of the presence of KRAS mutations." (PMID 38519578, 2024). "In addition, the B-RAF- and KRAS-driven colon cancer cells used in our analyses were “addicted to autophagy” because they overexpressed the hypoxia-inducible factors HIF-1α, HIF-2α, and HIF-3α, which promote autophagy." (PMID 38473963, 2024). "Considering the frequent presence of activating mutations in the KRAS proto-oncogene among MM and MGUS patients, with implications for disease prognosis, it is noteworthy that USP39 has been implicated in the development of KRAS-driven lung and colon cancers." (PMID 39736693, 2024). "Most KRAS-mutant colon cancers tend to occur in the context of APC mutation, suggesting that profound Wnt activation might be a key dependency for KRAS mutation." (PMID 38360902, 2024). "Thus far, identification of putative resistance mechanisms to KRAS inhibition has largely relied on sequencing circulating tumor DNA (ctDNA) from relapsed lung and colon cancer patients, using targeted gene panels." (PMID 38800401, 2024). "In addition to its direct inhibitory effect on KRAS-mutant cancer cells, sotorasib was found to promote antitumor immunity in a syngeneic CT-26 KRAS G12C colon cancer model by creating a pro-inflammatory tumor microenvironment." (PMID 38668053, 2024). "There are several ongoing clinical trials registered on the ClinicalTrials.gov website that investigate the use of EVs as therapeutic interventions for head and neck cancer (NCT03109873, NCT01668849), colon cancer (NCT01294072), and metastatic pancreatic cancer with KRAS G12D mutation (NCT03608631)." (PMID 38476233, 2024). "Notably, inhibition of TAK1 was found to induce apoptosis in KRAS-dependent colon cancers, further emphasizing its significance as a therapeutic target in this context." (PMID 39474417, 2024). "In various cancers, including colon cancer, melanoma, and thyroid cancer, tumors harboring mutations in the KRAS (Kirsten rat sarcoma viral oncogene homolog) and BRAF (encoding B-Raf protein) genes tend to be associated with a more aggressive behavior compared to wild-type tumors." (PMID 38391958, 2024).
colon carcinoma (continued). "Therefore, inhibition of the mitochondrial pathway can inhibit the growth of KRAS gene mutant cancer cells, which provides a new therapeutic target for the treatment of K-ras mutant colon cancer." (PMID 37020597, 2023). "However, inhibition of IL-17A in mice bearing KRAS-mutant lung tumors or transplantable colon cancer cell lines has provided proof-of-principle that targeting IL-17A in combination with anti–PD-1 is a viable strategy for controlling tumor growth." (PMID 36480166, 2023). "The findings also indicated that diabetic patients with a mutated KRAS gene had a higher risk of colon cancer than non-diabetics." (PMID 37175192, 2023). "These alterations were detected in 9 NSCLC samples (2 ALK rearrangements and 5 EGFR mutations, 1 BRAF mutation, and 1 G12C/KRAS mutation); 7 breast cancer samples (7 HER2 amplifications); 5 colon cancer samples (5 KRAS mutations); and 3 gastric cancer samples (2 MSI-high and 1 HER2 amplification)." (PMID 36832270, 2023). "Similar findings have been reported in colon cancer cells with mutant KRAS proteins." (PMID 37175872, 2023). "Taken together, these outcomes suggest that SVCT-2 expression may enable bypassing resistance to cetuximab in human colon cancer patients with a mutant KRAS by L-ascorbic acid." (PMID 36979659, 2023). "In many studies, KRAS mutation incidence was higher in right-sided than in left-sided colon tumors and higher in women but not for NRAS mutation." (PMID 37277698, 2023). "However, cells obtained from M1 stage patients presented a significantly higher KRAS OE score which suggested KRAS signature was related to distant metastasis of colon cancer." (PMID 38097680, 2023). "Although these features characterize the sessile serrated pathway (SSP) of colon cancers, other studies have shown that Fn infection is associated with KRAS mutations mainly characteristic of non-serrated neoplasia." (PMID 37772997, 2023). "KRAS is the most commonly mutated oncogene in colon cancer patients, and there are no clinically proven strategies for the treatment of KRAS-driven CRC." (PMID 37355626, 2023). "However, there are few studies on the application of KRAS related signature in predicting prognosis and drug sensitivity of colon cancer patient." (PMID 38097680, 2023). "Consequently, the kinase-independent role of CRAF is pivotal when considering combination therapies targeting KRAS-driven colon cancer." (PMID 38111008, 2023). "Moreover, in an in vivo colon cancer model, they demonstrated a significant reduction in tumor growth for the animals treated with the micelles encapsulating the anti-KRAS antibody in comparison with the animals receiving the empty micelles." (PMID 37376135, 2023). "Previously, Furin inactivation was found to impair the malignant phenotype of colon cancer cells with activating KRAS or BRAF mutations but not with wild-type (WT) KRAS or BRAF." (PMID 35267511, 2022). "OA induced the phosphorylation of ACLY in the KRas-driven colon cancer cell line HCT116 at S455." (PMID 36269753, 2022). "In case of progression, Docetaxel is added (except colon cancer), with or without Mitomycin C, and next cetuximab (except pancreatic and KRAS BRAF mutation cancers)." (PMID 36322580, 2022). "As a crucial driver of colon cancer development, KRAS-related signaling is enriched in glycolysis." (PMID 36569910, 2022). "All KRAS mutant colon cancer models were insensitive to EGFR inhibition." (PMID 35368031, 2022). "Furthermore, a recent study has presented combined CHK1 and topoisomerase inhibition as an effective combination in KRAS mutant colon cancer." (PMID 36237330, 2022).